NAMPT (nicotinamide phosphoribosyltransferase)
Diseases named in the same sentence as NAMPT in open-access papers (continued):
Sharing a sentence is not in itself a finding about the gene and the disease.
lymphoma (16 papers, 2017 to 2025). A malignant (clonal) proliferation of B- lymphocytes or T- lymphocytes which involves the lymph nodes, bone marrow and/or extranodal sites. "In LDHA-dependent lymphoma models, combinatory treatment of NAMPT inhibition and the LDHA inhibitor FX11 induced tumor regression in in vivo xenograft models." (PMID 40390151, 2025). "OT-82 induced cell death through NAMPT inhibition in vitro and in mouse xenograft models of hematopoietic malignancies, and it was used in phase I trials for relapsed or refractory lymphoma (NCT03921879)." (PMID 39337621, 2024). "In an effort to discover new anticancer agents, we here have identified three novel NAMPT inhibitors with broad and strong anti-leukemic/lymphoma activity." (PMID 36838885, 2023). "NAMPT overexpression has been found in various types of malignancy, such as acute-type adult T-cell leukemia/lymphoma cells and breast, thyroid, endometrial, bladder, pancreatic, colorectal, gastric, and prostate cancers." (PMID 36233428, 2022). "Here, we show that p21-activated kinase 4 (PAK4) and nicotinamide phosphoribosyl transferase (NAMPT) is critical for lymphoma subsistence." (PMID 35008323, 2021). "Interestingly, a previous study showed that a NAMPT inhibitor induced apoptosis accompanied by activation of caspases, DNA fragmentation, and disruption of mitochondrial transmembrane potential, in primary adult T-cell leukemia/lymphoma (which shows high expression of NAMPT)." (PMID 36658296, 2023). "This pathway is governed by nicotinamide phosphoribosyltransferase (NAMPT), an enzyme that is overexpressed in diverse malignancies, including neuroendocrine tumors, lymphomas, and adrenocortical carcinomas." (PMID 40654575, 2025). "The orally available NAMPT inhibitors KPT-9274 and OT-82 have been tested as potential drugs in patients with solid tumors or with relapsed/refractory lymphoma." (PMID 36838885, 2023). "Targeting visfatin (or NAMPT) as anti-inflammatory therapy has been shown to be effective in clinical trials on NAMPT inhibitors (such as FK866) in melanoma and lymphomas." (PMID 34639186, 2021). "Given the role of NAMPT and PAK4 in lymphoma biology, dual inhibition of NAMPT-PAK4 appears to be a promising therapeutic strategy." (PMID 35008323, 2021). "In highly glycolytic tumors, such as lymphoma, the combination of an LDHA inhibitor and a NAMPT inhibitor resulted in a synergistic anticancer effect." (PMID 29541451, 2018). "Notably, compound 3 induced the regression of lymphoma in combination with Daporinad (FK866 or APO866), a metabolic inhibitor of nicotinamide phosphoribosyltransferase (NAMPT), which is an enzyme involved in the biosynthesis of nicotinamide adenine dinucleotide (NAD+) from nicotinamide." (PMID 38731601, 2024).
lung carcinoma (15 papers, 2012 to 2024). "This group went on to show that multiple N-MYC amplified neoplasms including lung cancer, medulloblastoma, neuroblastoma, and Burkitt’s lymphoma were susceptible to NAMPT inhibition with GMX1778 at nanomolar concentrations." (PMID 35814452, 2022). "NAMPT is frequently studied in lung cancer, particularly in NSCLC, and it is considered a potential target of treatment, as well as a prognostic biomarker." (PMID 36674438, 2023). "Another lung cancer study indicated that NAMPT could promote migration, invasion, and wound closure, which concurred with the induced increase of MMP-2 and MMP-9 in H358 and A549 cells." (PMID 35565188, 2022). "We used A549 human lung carcinoma cells for routine testing of NAMPT activators." (PMID 31324777, 2019). "NAMPT (also known as pre-B-cell colony-enhancing factor or visfatin) is a pro-inflammatory adipocytokine which plays a major role in the up-regulation of NF-κB-mediated matrix metalloproteinase expression in lung cancer and promotes the migration and invasion of tumor cells." (PMID 29050246, 2017). "In silico and qRT-PCR analysis clearly supported the notion that, NRF2 directly binds to the ARE sequences located in the promoter regions of ALDH3B1, NAMPT, and PTGES genes and induces their expression in lung cancer." (PMID 29050246, 2017). "The HIF, TGM2, CSNK1A1, CSNK2A1, CTNNA1, NAMPT)/Visfatin, TNFRSF1A, ETS1 and SRC-1 were down-regulated and proposed as the biomarkers for lung cancer." (PMID 23122428, 2012). "Expression analysis reveals that hypoxia induced lung cancer related biomarkers, HIF and its modulating proteins (TGM2, CSNK1A1, CTNNA1, NAMPT/Visfatin, TNFRSF1A, ETS1, SRC-1, FN1, APLP2, DMBT1/SAG, AIB1 and AZIN1) are significantly down regulated." (PMID 23122428, 2012). "To further validate the putative hypothesis that NMN inhibits lung cancer growth through its metabolite NAM, we indirectly manipulated the amount of intracellular NAM by regulating the expression of catalyst NAMPT." (PMID 37173894, 2023).
rheumatoid arthritis (15 papers, 2008 to 2025). A chronic, systemic autoimmune disorder characterized by inflammation in the synovial membranes and articular surfaces. "Abnormal circulating levels of NAMPT were associated with various musculoskeletal disorders such as osteoporosis, osteoarthritis, and rheumatoid arthritis, suggesting an emerging role of NAMPT as an important biomarker and therapeutic target." (PMID 36443772, 2022). "Dysregulation of NAMPT has been associated with several inflammatory diseases, including rheumatoid arthritis (RA)." (PMID 30774990, 2019). "Compared to normal control subjects, higher concentration of circulating NAMPT was also observed in rheumatoid arthritis, osteoarthritis, and osteoporosis." (PMID 36443772, 2022). "In line with this, NAMPT was shown to be a marker of chronic diseases like inflammatory bowel diseases or rheumatoid arthritis further suggesting that NAMPT is involved in the regulation of inflammation." (PMID 28837586, 2017). "On the other hand, eNAMPT, mostly in the form of serum NAMPT, likely functions as a potential inflammatory cytokine in diverse biological contexts, including acute lung injury, cancer, rheumatoid arthritis, atherosclerosis, and heart failure." (PMID 26389889, 2015). "Since its expression is upregulated during inflammation, NAMPT represents a novel clinical biomarker in acute lung injury, rheumatoid arthritis, and Crohn's disease." (PMID 18493620, 2008). "Moreover, NAMPT is systemically elevated in patients with rheumatoid arthritis or inflammatory bowel diseases." (PMID 34202251, 2021). "Furthermore, the dysregulation of NAMPT expression is reported to be associated with several diseases with inflammation as the major pathological factor, and early research has reported elevated NAMPT levels in patients with rheumatoid arthritis, putting forward it as one of the biomarkers in RA." (PMID 41021591, 2025). "The glycolytic regulator NAMPT has been identified as a therapeutic target of rheumatoid arthritis (RA), while other metabolic regulators coordinating NAMPT to perpetuate inflammation are yet to be investigated." (PMID 35111160, 2021).
Sepsis (15 papers, 2012 to 2025). Sepsis is defined as life-threatening organ dysfunction caused by a dysregulated host response to infection. "NAMPT signalling identified in this study may be a novel therapeutic target for mitigating systemic inflammation and kidney injury associated with severe sepsis." (PMID 39568061, 2025). "Notably, previous studies have linked the serum level of NAMPT to the prognosis of patients with sepsis." (PMID 39568061, 2025). "This study uncovered the NAMPT signalling pathway from the CD38-positive macrophages to the renal stromal cells in a mouse model of sepsis and validated these findings in human samples." (PMID 39568061, 2025). "This study, for the first time, presents evidence regarding elevated NAMPT expression in the kidneys of patients with sepsis." (PMID 39568061, 2025). "Elevated plasma NAMPT had been reported in patients with infectious diseases, such as sepsis, pneumonia, COPD, and acute lung injury." (PMID 34702907, 2021). "MiR-96-5p was low expressed while nicotinamide phosphoribosyltransferase (NAMPT) was high expressed in the serum of neonatal septicemia patients." (PMID 32618342, 2020). "MiR-96-5p alleviated inflammatory responses via targeting NAMPT and inhibiting NF-κB pathway in neonatal sepsis." (PMID 32618342, 2020). "In the present study, we found NAMPT expression was increased in the serum of neonatal sepsis patients and induced by LPS in RAW264.7 cells." (PMID 32618342, 2020). "In a mouse model of sepsis, overexpression of miR-300 augmented autophagy by targeting nicotinamide phosphoribosyltransferase (NAMPT), activating the AMPK signaling pathway, and inhibiting cell apoptosis." (PMID 31507440, 2019). "Given that several NAMPT inhibitors have been developed as anti-cancer agents, we propose that these inhibitors could potentially be repurposed for the treatment of sepsis." (PMID 39568061, 2025). "In addition, previous studies have indicated that NAMPT inhibition by FK866 can alleviate sepsis-induced neuroinflammation and lung injury in mouse models." (PMID 39568061, 2025). "During inflammation, NAMPT (nicotinamide phosphoribosyltransferase a crucial regulator of NAD+ production, supports the energy-intensive mechanisms underlying cytokine synthesis and immune cell activity, which are significantly elevated in sepsis." (PMID 41303672, 2025). "In contrast, the expression of NAMPT was up-regulated serum of neonatal sepsis patients." (PMID 32618342, 2020). "Therefore, NAMPT signalling may be a novel therapeutic target for sepsis-induced kidney injury and systemic inflammation." (PMID 39568061, 2025). "To confirm this, we used an NAMPT inhibitor, FK866, in this sepsis model and observed that FK866 significantly attenuated kidney injury and IL-6 production induced by LPS and CD38 ligation." (PMID 39568061, 2025). "In sepsis-induced ALI patients, elevated plasma nicotinamide phosphoribosyl transferase (NAMPT) levels induce T cells pyroptosis and immune dysfunction, which can be alleviated by the NAMPT inhibitor FK886." (PMID 40822495, 2025). "However, the origin and targets of NAMPT in sepsis have not yet been elucidated." (PMID 39568061, 2025).
atherosclerosis (14 papers, 2012 to 2025). A disease characterized by the build-up of fatty material and calcium deposition in the arterial wall resulting in partial or complete occlusion of the arterial lumen. "The overexpression of NAMPT has been associated with inflammatory processes and the development of various human conditions, including acute lung injury, atherosclerosis, and cancer." (PMID 38134282, 2023). "Recent studies also identify NAMPT as underlying an aging suppression pathway in smooth muscle cells, with potential relevance to controlling atherosclerosis and possibly other diseases of aging." (PMID 25926556, 2015). "NAMPT has emerged in the last few years as a novel adipokine potentially implicated in the pathogenesis of atherosclerosis." (PMID 23968400, 2013). "Therefore, the objective of this study was to use a NAMPT loss-of-function approach to investigate the effect of NAMPT on atherosclerosis in hypercholesterolemic mice." (PMID 27229177, 2016). "Studies in different populations, including a meta-analysis, suggested that high levels of circulating NAMPT are positively associated with cardiovascular disease and atherosclerosis-related metabolic phenotypes, as well as with the 10-year CVD Framingham risk score." (PMID 23968400, 2013). "In conclusion, NAMPT is a critical therapeutic target of Alisol A in the treatment of atherosclerosis-related vascular cognitive impairment." (PMID 41041049, 2025). "Analysis of GEO datasets showed that NAMPT expression was most markedly altered in atherosclerosis patient samples (P < 0.01)." (PMID 41041049, 2025). "NAMPT, the rate-limiting enzyme of NAD + salvage biosynthesis, is considered to be associated with atherosclerosis." (PMID 38974325, 2024). "NAMPT has also been implicated in mediation of other inflammatory conditions including neuroinflammation, atherosclerosis, and arthritis, and future work will take a closer look at the relevance of Stat1-induced NAMPT in these settings." (PMID 33976173, 2021). "Conversely, NAMPT overexpression aggravated atherosclerotic inflammation and enhanced atherosclerosis development in Apoe−/− mice." (PMID 34943043, 2021). "In summary, this study has provided new information with respect to the role of NAMPT in the development of atherosclerosis." (PMID 27229177, 2016). "In contrast, global NAMPT overexpression aggravated atherosclerosis in ApoE−/− mice." (PMID 38974325, 2024). "This led us to investigate whether NAMPT knockdown affected cholesterol metabolism and the development of atherosclerosis." (PMID 27229177, 2016). "Several of the differentially regulated genes are involved in vascular pathophysiology; for example: DNAJB6 and DUSP1 (atherosclerosis), NAMPT (vascular inflammation), FCAR (myocardial infarction), IL8 (vascular remodelling), FFAR2 (lipid metabolism) and SOD2 (idiopathic cardiomyopathy (IDC))." (PMID 22409835, 2012). "Visfatin is a new identified adipokine that plays a role as a proinflammatory mediator in the process of atherosclerosis and also in plaque destabilization, also known as NAMPT (nicotinamide phosphoribosyltransferase) and PBEF (pre-beta cell-enhancing factor)." (PMID 30405857, 2018). "Here, NAMPT knockdown seemed to exert contradictory effects in these experiments, protecting against atherosclerosis without changing insulin sensitivity." (PMID 27229177, 2016). "The lack of knock-out mouse of NAMPT has made it difficult to systematically investigate the role of NAMPT in the development of IR and atherosclerosis." (PMID 27229177, 2016).
atherosclerosis (continued). "Recently, whether extracellular NAMPT could promote M2 skewing in atherosclerosis models and how NAMPT regulates macrophage polarization are not completely understood and more researches on them are expected." (PMID 30923552, 2019). "Our results indicate that NAMPT knockdown exerts antiatherogenic effects by promoting macrophage RCT through the PPARα-LXRα pathway, and is consistent with the concept that NAMPT may be a negative regulator of macrophage RCT and the development of atherosclerosis in humans." (PMID 27229177, 2016). "As the outcome of numerous studies has shown that the rate of macrophage RCT has a greater influence on the degree of atherosclerosis than the levels of HDL-C24, this increase in RCT could be primarily responsible for the positive effects of NAMPT knockdown on atherosclerosis." (PMID 27229177, 2016).
Hepatic steatosis (13 papers, 2017 to 2026). Steatosis is a term used to denote lipid accumulation within hepatocytes. "Since SIRT1 has been shown to regulate ethanol-induced liver steatosis, we hypothesized that increased NAD+ production and SIRT1 activity caused by NAMPT overexpression contributed to the alleviation of ethanol-induced hepatic steatosis." (PMID 30794635, 2019). "The intracellular NAMPT inhibitor FK866 promoted liver steatosis in HFD-fed mice and hepatic lipid accumulation in vitro via the sirtuin 1 (SIRT1)/sterol regulatory element-binding protein 1 (SREBP1)/fatty acid synthase (FASN) pathway." (PMID 36009862, 2022). "NAMPT was also shown tobe reduced in the liver tissue of patients with NAFLD,further confirming the relationship between NAMPT and hepatic steatosis." (PMID 32779442, 2020). "In agreement with our results in NRK1 deficient mice, depletion of hepatic NAD+ pool via the expression of a dominant negative form of NAMPT also results in hepatic steatosis and insulin resistance." (PMID 31541116, 2019). "In a chronic and binge ethanol feeding mouse model, adenovirus-mediated NAMPT transduction in liver cells significantly protects against ethanol-induced hepatic steatosis and injury." (PMID 30794635, 2019). "Taken together, our data suggest that SIRT1 is the major sirtuin family member to mediate NAMPT’s role in alleviating ethanol-induced liver steatosis and injury." (PMID 30794635, 2019). "Our results demonstrated that inhibition of NAMPT aggravated the HFD- or oleic acid-induced hepatic steatosis through suppressing Sirt1-mediated signaling pathway." (PMID 28449683, 2017). "The findings of this study will broad our understanding of the roles of NAMPT in hepatic lipid metabolism and provide important insights in targeting NAMPT for treating liver steatosis and NAFLD." (PMID 28449683, 2017). "Our results suggested that NAMPT played a critical role in hepatic steatosis model in vivo and in vitro." (PMID 28449683, 2017). "In order to determine whether NAMPT is involvedin hepatic steatosis, Oil Red O staining was performed.The results indicated that lipid content of HepG2 cellswas significantly increased after NAMPT knockdown." (PMID 32779442, 2020). "Similarly, adenovirus-mediated overexpression of NAMPT in mice ameliorates ethanol induced hepatic steatosis." (PMID 30794635, 2019). "To test whether SIRT6 mediates the effects of NAMPT on ethanol-induced liver steatosis, we also used adenovirus to overexpress NAMPT-HA in the livers of Sirt6-HepKO mice fed with ethanol." (PMID 30794635, 2019). "Therefore,increased gene expression of SREBP-1 as well as FAS mightserve as another mechanism linking NAMPT to hepatic steatosis." (PMID 32779442, 2020). "Ethanol has been revealed to inhibit NAMPT expression in the liver, while NAMPT overexpression can significantly elevate intracellular NAD+ levels, thereby alleviating ethanol-induced hepatic steatosis in mice." (PMID 40819082, 2025). "NAMPT can mediate the activity of NAD+-dependent enzymes and alleviates hepatic steatosis in a SIRT-dependent manner in mice." (PMID 37891928, 2023). "More recently, we found that inhibition of NAMPT, a rate-limiting enzyme regulated NAD+ biosynthesis, aggravated HFD-induced hepatic steatosis." (PMID 34803499, 2021). "In this study, we showed for the first time that NAMPT overexpression is an alternative way to enhance NAD+ biosynthesis and alleviate ethanol-induced fatty liver." (PMID 30794635, 2019). "In this study, we showed that adenovirus-mediated hepatic overexpression of NAMPT increased NAD+ levels and thereby alleviated ethanol-induced liver steatosis." (PMID 30794635, 2019). "To further confirm the role of NAMPT in hepatic lipid metabolism, we first examined the effects of FK866, a highly specific NAMPT inhibitor, on HFD-induced hepatic steatosis." (PMID 28449683, 2017).